CAT (catalase)
Diseases named in the same sentence as CAT in open-access papers (continued):
Sharing a sentence is not in itself a finding about the gene and the disease.
diabetes (continued). "On the cellular level, we demonstrated a dose-dependent downregulation of cytokines, chemokines and NOX isoforms by hidrosmin in VSMC exposed to hyperglycemia, as well as SOD1 and catalase upregulation, thus confirming its anti-inflammatory and antioxidant action in the diabetes context." (PMID 36552707, 2022). "In addition, we found the enzyme CAT to be a candidate for predicting diabetes, with a high sensitivity, specificity, and AUC, similar to HbA1c." (PMID 36139749, 2022). "miR-21, SOD, CAT, and IL-6 revealed a high predictive value for diabetes diagnosis." (PMID 36139749, 2022). "Several studies showed that the activity of CAT in patients with diabetes decreased significantly compared with healthy people and led to microvascular complications (e.g., diabetic retinopathy) in patients with diabetes." (PMID 35480487, 2022). "Therefore, lipid peroxidation, reduction of GSH content, and inhibition of SOD and catalase activity are very important in the treatment of diabetes and related disorders." (PMID 35208513, 2022). "Polymorphisms in involved proteins such as superoxide dismutase (SOD), catalase (CAT), and glutathione peroxidase (GPX) were associated with various human metabolic disorders such as diabetes, CVD, and cancer, emphasizing the critical role of enzymatic antioxidant systems." (PMID 35821802, 2022). "Overall, c-miR-21, SOD, CAT, and IL-6 had high predictive values for diabetes diagnoses." (PMID 36139749, 2022). "In particular, in a study conducted on patients with acute coronary syndrome and concomitant diabetes mellitus type 2, lisinopril induced changes in antioxidant defense, increasing catalase activity, lowering blood creatinine, and eliminating protein in the urine." (PMID 35656292, 2022). "Thus, the ROC curve analysis suggested that CAT activity changes give it high predictive power for diabetes." (PMID 36139749, 2022). "In streptozotocin-induced gestational diabetes in rats, caffeic acid (in a dose-dependent manner) normalized fetus weight, blood lipids, and antioxidant enzymes superoxide dismutase (SOD), glutathione peroxidase (GPX), catalase (CAT), and glutathione negatively altered by diabetes." (PMID 36614030, 2022). "Previous reports have indeed shown decreased level of CAT after the onset of diabetes mellitus." (PMID 34356475, 2021). "The colocalization of incretins with catalase suggests that these cytoprotective proteins may be working together to combat diabetes-induced oxidative stress." (PMID 34440748, 2021). "As antioxidant enzyme activities are associated with ROS concentration, the possible reason of the current results is that, during the six weeks, ROS production attributable to diabetes was just slightly increased and had stimulated the rise of CAT and SOD activities." (PMID 34993484, 2021). "A slight of ROS can be eliminated quickly by antioxidant substances (such as superoxide dismutase, catalase, and glutathione peroxidase) in the tissues, while in diabetes mellitus, the increases of pro-oxidants and the reduction of antioxidants lead to an excessive production in ROS." (PMID 33688363, 2021). "We found significantly increased activity of catalase and GPx in diabetes." (PMID 34573031, 2021). "Since oxidative stress is the main risk factor of hemolysis of the red blood cells and anemia due to diabetes, the improvement of hematological indices can be attributed to the antioxidant properties of A. saralicum extract on controlling catalase and superoxide dismutase enzymes." (PMID 34531994, 2021). "The activity of catalase increased by 4.29 times in blood plasma under diabetes." (PMID 34573031, 2021). "Thus, the enhancement of lipid peroxidation and reductions of endogenous antioxidants, GSH content, and SOD and CAT activities that occur in damaged liver tissue are secondary considerations in terms of improving diabetes and related problems." (PMID 32947952, 2020). "For CAT rs1001179, there are two significant studies of its impact on diabetes." (PMID 33138337, 2020).
diabetes (continued). "Also, induction of diabetes by administration of STZ significantly increased the activity of catalase in the hearts of untreated diabetic rats." (PMID 32046294, 2020). "Mice genetically overexpressing or deleting catalase reveal that catalase is also involved in various physiological and pathological processes such as renal injury and cardiomyocyte dysfunction in diabetes." (PMID 32831175, 2020). "Functionally, NGEN reduces free radicals like ROS and enhances antioxidant activity such as catalase, superoxide dismutase, glutathione in chronic diseases, including neurodegenerative disease, cardiovascular disease, diabetes, pulmonary disease, cancer and nephropathy." (PMID 32667124, 2020). "However, the changes of GPx and catalase levels in diabetes with glucose fluctuations are still unclear." (PMID 31620092, 2019). "As already discussed, catalase is interconnected to diabetes mellitus pathogenesis." (PMID 31827713, 2019). "On the other hand, while SOD seems to be decreased in diabetes, catalase has been shown to be elevated, suggesting that H2O2 may be the predominant source of oxidative stress in diabetes." (PMID 30373222, 2018). "CAT rs7943316 and GPX-1 rs1050450 polymorphisms alter their antioxidant capacity and associated with different kinds of diseases such as Kashin-Beck, prostate cancer, peripheral neuropathy, diabetes mellitus recurrent miscarriage, and brain tumors." (PMID 30524988, 2018). "The increase in GSH and CAT activity with TQ administration may reduce oxidative stress in diabetes mellitus." (PMID 29743967, 2018). "Interestingly, patients with catalase gene mutation have life‐long increased H2O2 concentration, which has cytotoxic effects on pancreatic cells, to be a risk factor for diabetes." (PMID 30132841, 2018). "This shows that diabetes suppresses CAT enzyme at the transcription level in renal tissues." (PMID 30602713, 2018). "However, CAT enzyme activity was significantly decreased, suggesting that post-transcriptional modifications occur in diabetes." (PMID 30622608, 2018). "Accordingly, CAT activity was significantly suppressed with diabetes (p < 0.05)." (PMID 30602713, 2018). "Besides, it ameliorated the dysfunction of antioxidant enzymes, including SOD, CAT, GPx, GST, and GR catalase, in diabetic kidneys." (PMID 30602713, 2018). "The results suggest that the plasma levels of CAT, TAC and reduced glutathione could give information on the risk of developing complications of diabetes, considering that the modification of these biomarkers levels were associated with oxidative stress." (PMID 28356165, 2017). "Furthermore, the diabetes‐induced increases in nuclear translocation of p65 and beclin‐1 expression were inhibited by catalase overexpression." (PMID 28643395, 2017). "However, the CAT activity of the control group was significantly lower compared to that of patients with diabetes." (PMID 28356165, 2017). "The activities of SOD and catalase are low in diabetes mellitus." (PMID 27047569, 2016). "An increase in the activities of catalase was reported in persons with diabetes." (PMID 25922827, 2015). "Furthermore, in diabetes induced animal models anti-oxidant enzymes catalase, GPx and super-oxide dismutase (SOD) are decreased than in normal animals." (PMID 26381880, 2015). "Short-term diabetes may also increase the myocardial content of free-radical scavenging enzymes, catalase, and glutathione reductase which may also be involved." (PMID 26229969, 2015). "Thus CAT and CuZnSOD examined in this study will be of little use in the diagnosis of early or latent of diabetes." (PMID 25649751, 2015). "So, the increased lipid peroxidation and decrease of endogenous antioxidants—GSH contents, and antioxidant active enzymes—SOD and CAT activities in the damaged liver tissue are of secondary importance in terms of helping improve diabetes and various related complications." (PMID 26540072, 2015).
diabetes (continued). "It should be noted that in the present study, diabetes also increased aortic Nrf2 expression and its downstream CAT and NQO-1 gene expression, which suggests that Nrf2 acts as a protective mechanism at certain early stages to be up-regulated with the attempt to protecting the tissue." (PMID 24720784, 2014). "Additionally, the activities of all detected anti-oxidant enzymes including SOD, GSH-PX and CAT were significantly diminished in diabetes-induced rats (p < 0.01) compared with controls." (PMID 24857910, 2014). "We have shown that activity of hippocampal antioxidant enzymes such as SOD, CAT, and GPx was decreased in diabetes which could contribute towards oxidative stress." (PMID 25161691, 2014). "Diabetes promoted an increase in catalase concentration (p < 0.05)." (PMID 25301475, 2014). "The antidiabetic activity was tested in mice following streptozotocin diabetes induction, and selected oxidative stress markers (Malondialdehyde, Hydrogen peroxides and Catalase) were measured in order to evaluate the level of oxidative stress in treated animals." (PMID 23855679, 2013). "Moreover, SOD and catalase activity were significantly increased during the early stage of diabetes in streptozotocin-treated rats." (PMID 20830306, 2010). "In the present study, diabetic control rats showed significant increase in TBARS levels and decrease in SOD, catalase and glutathione levels in the rat liver homogenates compared to normal rats, indicating a dysfunction in antioxidant defensive system in diabetes mellitus." (PMID 20431798, 2010). "At the end of four weeks, eight weeks, and 13 weeks, animals were killed and components involved in the pathogenesis of diabetic cataract including thiols (from glutathione and protein), glutathione reductase (GR), catalase (CAT), and glycated proteins were investigated in the lens extracts." (PMID 18490958, 2008). "The association of carvacrol with magnolol (PDCM group) demonstrated a significant decrease in MDA values (p < 0.05) and a non-significant increase in CAT values in the blood of rats with periodontitis associated with diabetes mellitus when compared to the PD group." (PMID 38132422, 2023). "However, due to reduced CAT activity, beta cells of the pancreas that contain many mitochondria undergo oxidative stress by producing excess ROS that leads to β-cells dysfunction and, ultimately, diabetes." (PMID 37763234, 2023). "Additionally, an antioxidant study revealed that Glc, along with both carriers, has a high potential as a free radical scavenger and may improve TAS, SOD, and CAT levels, which are reduced in diabetics." (PMID 36466089, 2022). "However, previous studies have indicated that in diabetes and asthma, loss in catalase activity was not correlated with any decrease in its protein expression level." (PMID 32911700, 2020). "We found that levels of SOD and catalase were increased and hydrogen peroxide was decreased in aortic tissues in fenofibrate-treated diabetic mice compared with vehicle-treated diabetic mice, which indicating an inhibition of oxidative stress by fenofibrate in diabetes." (PMID 30296701, 2019). "Antioxidative treatment will play a larger role in the treatment of diabetes and has a promising future, which may increase intracellular antioxidative agents such as catalase (CAT) and superoxide dismutase (SOD) and eliminate lipid peroxide malondialdehyde (MDA)." (PMID 30941199, 2019).
diabetes (continued). "However, CAT level decreased in diabetes (P<0.001), groups IV (P<0.01), VI (P<0.001), VIII and IX (P<0.05) when compared to control, but this variable increased in groups II (P<0.001), IV (P<0.05), V (P<0.001), VII, VIII (P<0.01), and IX (P<0.01) versus diabetes group." (PMID 32133060, 2019). "Melatonin was found to increase the inhibited activity of catalase in rat liver cells and restore the dysfunctional mitochondria related to diabetes at the dose of 10 mg/kg, indicating melatonin could be a beneficial option to treat diabetes." (PMID 28387721, 2017). "In addition, high‐glucose‐induced activation of autophagic flux and apoptosis were largely attenuated by p65 siRNA, suggesting that catalase ameliorates diabetes‐induced autophagy, at least in part by increasing the activity of the NF‐κB pathway and p65‐mediated transcription of BECN1." (PMID 28643395, 2017). "Two antioxidant markers from liver namely malondialdehyde (MDA) and catalase (CAT) were selected since they are known to play an important role in neutralizing the effect of reactive oxygen species (ROS) thatare generated due to pathological conditions like diabetes." (PMID 28085064, 2017). "However, oxidative stress might develop in the long term in a chronic picture of diabetes and lead to tissue injury in addition to reduction in catalase and GST activity." (PMID 22536214, 2012). "In rats with STZ-induced diabetes, blood SOD, CAT, and GPx activities were reduced, while malondialdehyde (MDA) levels, the end product of lipid peroxidation, were elevated." (PMID 40806520, 2025). "In mice with diabetes induced by the administration of alloxan (ALX), skeletal muscle showed reduced activities of antioxidative enzymes, SOD and CAT, and a concomitant decrease in GSH content." (PMID 40806520, 2025). "In rats with diabetes induced by the administration of STZ, pancreatic activities of antioxidant enzymes (CAT, SOD, and GPx) were reduced, while MDA levels were elevated." (PMID 40806520, 2025). "Diabetes-related oxidative stress was accompanied by the decreased hepatic activity of SOD and CAT, as well as the reduced content of glutathione (GSH)." (PMID 40806520, 2025). "Our investigation revealed that diabetes dramatically enhanced MDA levels and decreased GSH concentration and the antioxidant enzyme activity of GPx and catalase." (PMID 39391856, 2024). "In a streptozotocin-induced rat model of diabetes, propolis decreased malondialdehyde (MDA) and elevated the activity of anti-oxidants such as glutathione (GSH), superoxide dismutase (SOD), and catalase (CAT)." (PMID 38419887, 2024). "In models of diabetes in animals, MDA plasma level and catalase activity increased and decreased meaningfully due to hyperglycaemia and oxidative stress induction as shown in the current research." (PMID 38528644, 2024). "This increase in reactive oxygen species negatively impacts the activity of key antioxidative enzymes, namely peroxidase, catalase, superoxide dismutase, and glutathione S-transferase (GST), in individuals with diabetes." (PMID 38603728, 2024). "In this study, the induction of diabetes resulted in a notable increase in MDA concentrations and a decrease in GSH, SOD, and CAT activity in the brain of untreated diabetic rats when compared to the control group." (PMID 39830570, 2024). "In diabetes condition, the results found with a significantly (p ≤ 0.001) high level of LPO and lower levels of GSH, CAT, SOD and GPX activity in animals." (PMID 38755663, 2024). "In this study, the oxidative stress marker MDA and two key antioxidant markers, GSH and catalase, were analyzed in brain samples to assess the potential of SITG in mitigating oxidative stress induced by diabetes in rats." (PMID 39766390, 2024). "The current study pointed out the significant decrease in the activities of catalase and SOD upon induction of diabetes compared to the normal control group." (PMID 37170684, 2023).
diabetes (continued). "Our results indicated that diabetes induced an appreciable release of Cyto-cyc in Leydig cells, which was consistent with the increase of ROS and the downregulation of GPX and CAT, indicating mitochondrial balance and oxidative stress." (PMID 36778206, 2023). "In comparison, administration of CTS-SeNPs or Glib in diabetics enhanced the levels of GSH, TAC, and CAT activity." (PMID 35237941, 2023). "SOD, catalase and MDA levels show that the induction of diabetes significantly (p < 0.05) decreased SOD and catalase and significantly (p < 0.05) increased MDA levels." (PMID 37065804, 2023). "The inhibition of CAT and SOD activity, reduction of GSH content, and lipid peroxidation are considered crucial for treating diabetes and its related complications." (PMID 38275632, 2023). "Compared with the diabetic group, LBPs promoted the production of antioxidant enzymes such as SOD, CAT, and GPx, while down-regulating Caspase-3 expression and up-regulating the ratio of Bcl-2/Bax in STZ-included diabetes mice." (PMID 37497112, 2023). "When significant focus was placed on the effect of pomegranate on oxidative stress in rodent models of diabetes, a few markers that were considered included MDA, SOD, CAT, TBARS, GSH, GPx, TAC/AOC, ROS, PON1, FFA, and lipid peroxidation." (PMID 37627561, 2023). "Green tea, being a ROS scavenger mediates reversal of the alcohol exacerbated diabetes-induced nitroxidative stress by increasing SOD and CAT activities, followed by reducing the levels of LPO, PC, NO, PXN in the different brain sections concomitantly." (PMID 37449181, 2023). "Where diabetes and periodontitis were induced, MDA was augmented and CAT was depleted significantly." (PMID 38132422, 2023). "Upon diabetes mellitus induction, SOD and CAT are greatly deactivated, likely due to histidine or lysine group modifications." (PMID 37999206, 2023). "In diabetes, antioxidant enzyme activities, namely superoxide dismutase (SOD), sirtuin (SIRT) 1, and catalase (CAT) decrease, resulting in the induction of oxidative stress and subsequent cellular damage." (PMID 38234970, 2023). "Diabetes suppressed antioxidant enzymes CAT, SOD, GPx and testosterone levels were significantly decreased, and increased MDA level in the diabetic group compared to diabetes+IE group (p < 0.001)." (PMID 37098926, 2023). "Long-term treatment of diabetes with high doses of Caralluma edulis extracts reversed the SOD and CAT functions, possibly due to decreasing oxidative stress as evidenced by a low level of lipid peroxidation." (PMID 36014583, 2022). "Catalase, GPx and GSH are antioxidant biomarkers imbalanced in diabetes due to the metabolic syndrome." (PMID 35739932, 2022). "The enzymatic activities of SOD, CAT, GSH, and GPX genes are significantly decreased in diabetes due to increased oxidative stress." (PMID 36552606, 2022). "STZ‐induced diabetes can lead to enhancement of MDA activity and lipid peroxidation, and it seems that antioxidant enzymes such as SOD, CAT and GPx were suppressed in testis tissue." (PMID 35527404, 2022). "Recent studies have shown increased MDA and decreased SOD, CAT, and GSH levels in kidney animals with diabetes than those in control kidneys." (PMID 36432138, 2022). "In diabetes, the activities of antioxidant defense enzymes such as SOD and CAT are responsible for scavenging free radicals and regulating redox homeostasis." (PMID 36386214, 2022). "STZ-induced diabetes significantly reduced the levels of pancreatic antioxidant enzymes such as SOD, GPx and CAT and increased the malondialdehyde (MDA) level in the DC group in comparison with the NC group." (PMID 36555498, 2022).